IL17A (interleukin 17A)
Diseases named in the same sentence as IL17A in open-access papers (continued):
Sharing a sentence is not in itself a finding about the gene and the disease.
psoriasis (continued). "Thus, we sought evidence for the existence of dual secreting IL-17A/IL-22 Th17 cells within the psoriasis transcriptome." (PMID 31019502, 2019). "Secukinumab was the first IL-17A inhibitor approved for psoriasis in 2015." (PMID 30909615, 2019). "Hence, our data identify keratinocyte-derived IκBζ as an essential mediator of IL-17A– and IL-36–dependent gene expression and a main driver of psoriasis pathogenesis." (PMID 31622280, 2019). "Furthermore, using a commonly used mouse model of psoriasis-like inflammation, we demonstrate that neutrophils have a major contribution to psoriasis-like inflammation heightening IL-17A and IL-36 responses, which is dependent upon NETs release and function." (PMID 31024570, 2019). "The present paradigm of psoriasis pathogenesis revolves around the IL-23/IL-17A axis." (PMID 31019502, 2019). "Almost 10 years ago, the first clinical trial data with secukinumab were published, and at an early stage it was obvious that the targeted treatment with IL-17A antagonists has a higher capability of improving psoriasis compared to established previous therapy options." (PMID 32010143, 2019). "IL-17A plays a leading role in the pathogenesis of psoriasis." (PMID 30744173, 2019). "In addition to keratinocytes, we were able to stimulate skin-resident immunocompetent cells in situ to produce IL-17A under culture conditions that mimicked the prevalent Th17/IL-23 cytokine profile in psoriasis." (PMID 30972071, 2019). "Secukinumab is an anti-IL-17A antibody approved for psoriasis treatment." (PMID 31186952, 2019). "Mechanistically, it is unclear whether this systemic inflammation is a consequence of the psoriasis-like skin inflammation or whether keratinocyte overexpression of IL-17A itself, which was also detectable in the blood, triggers the systemic effects." (PMID 31622280, 2019). "Interestingly, TNFα, INFγ, and IL-17A, which are the main effector of the Th1/Th17 response in psoriasis pathogenesis, also resulted to stimulate the IL-33 release." (PMID 31736655, 2019). "IL17A-targeting antibodies show an impressive clinical efficacy in patients with psoriasis." (PMID 32010143, 2019). "The best studied inflammatory skin disease with a predominant role of IL-17A is psoriasis." (PMID 32010143, 2019). "Although dual-secreting T cells may exist, our results demonstrate that it is unlikely that the classical Th17 cells (IL-17A/ IL-22 dual-secreting T cells) play a universal role in psoriasis pathophysiology." (PMID 31019502, 2019). "However, it is important to note that untreated GILZ−/− mice have increases in IL-17A and IL-22 producing lymphocytes and that the contribution of these basal alterations to the disease elicited in the psoriasis model is unclear." (PMID 31572404, 2019). "No variants in the IL-17A gene itself was shown to predispose to psoriasis so far, whereas the IL-17RA allele rs4819554 was recently associated with risk of developing psoriasis in a Spanish cohort." (PMID 30127781, 2018). "IL-17A has been well characterized as one of the major drivers for psoriasis pathogenesis whereas IL-17F shares some redundant functions to IL-17A but its role in psoriasis is less defined." (PMID 30185226, 2018). "For several years, it was hypothesized that the primary source of IL-17A in psoriasis was T helper 17 (Th17) cells." (PMID 30109481, 2018). "This article reviews the immunologic role of interleukin (IL)-17, the major effector cytokine in the pathogenesis of psoriatic disease, along with the rationale for targeting the IL-17 cytokine family (IL-17A, IL-17F, and IL-17 receptor A) in the treatment of psoriasis and psoriatic arthritis." (PMID 30109481, 2018). "We subsequently investigated whether neutrophils isolated from patients with active psoriasis could express/produce IL-17A, IL-17F, and/or IL-17RC mRNA, either constitutively or upon incubation for 20 h with IFNγ plus LPS, R848, or IL-17A." (PMID 29719541, 2018).
psoriasis (continued). "Moreover, neutrophils were identified as the numerically largest source of IL-17A in psoriasis along with Th17 cells." (PMID 30279326, 2018). "In addition, other studies have shown the therapeutic role of autophagy in psoriasis via inhibition of IL-17a production." (PMID 30108582, 2018). "IL-17A and IL-17F are clinically validated mediators of psoriasis." (PMID 30013558, 2018). "IL-17A is the most important of the six known IL-17 isoforms for the pathophysiology of psoriasis." (PMID 29963046, 2018). "In this study, we found that Notch1 inhibition by DAPT can obviously reduce splenic Th17 cell population, mRNA expression of Th17 cell specific transcription factor RORγt, as well as IL-17A mRNA expression and serum concentration in the mouse model of psoriasis-like skin inflammation." (PMID 29523162, 2018). "In psoriasis, inhibitors of IL-17A axis bring a clear benefit in patient care management." (PMID 30693283, 2018). "Since IL-17A-producing cells are of critical importance in psoriasis and probably also in other chronic inflammatory diseases such as AD and SLE20, we wanted to confirm the production of IL-17A on the protein level and identify the cells producing this cytokine." (PMID 29650963, 2018). "Additionally, anti-IL-17A monoclonal antibodies prevented vascular disease in a murine model of psoriasis." (PMID 30109481, 2018). "Inhibition of IL-17A, IL-17 receptor A, or simultaneous inhibition of IL-17A and IL-17F leads to disruption of signaling pathways critical to the development and maintenance of psoriasis." (PMID 30109481, 2018). "IL-17A acts in synergism with other key-cytokines in psoriasis such as TNF-α and IL-22, stimulating the expression AMPs (LL37, β-defensins, LCN2, S110A family proteins), inflammatory cytokines (IL-1 family members and IL-6), and chemokines (CXL1, -3, -5, -8, and CCL20)." (PMID 29316717, 2018). "To date, it is evident that many other cells contribute to the bulk of IL-17A found in the diseased skin, and that many isoforms of IL-17 may participate to psoriasis." (PMID 30127781, 2018). "IL-17A–producing and RORγt-positive γδ T cells are crucial for proper development of psoriasis." (PMID 29985916, 2018). "IL-23 and IL-17A are key inflammatory cytokines in psoriasis pathogenesis." (PMID 30109481, 2018). "Our results showed that topical application of PG102 ameliorates clinical symptoms of psoriasis, reducing skin thickness and Interleukin (IL)-17A level in draining lymph nodes without causing any adverse effects." (PMID 30279326, 2018). "Notably, the “Role of IL-17A in Psoriasis” (T2, −log(FDR) = 1.67) pathway was enriched, in which downregulated CXCL3, IL-8, S100A8, S100A9, IL17RA and CXCL1 expression was observed." (PMID 29871627, 2018). "In psoriasis, pro-inflammatory cytokines including IL-17A, IL-22, TNF-α and IL-1α may contribute to the pathophysiology of the disease." (PMID 30180891, 2018). "Likewise, in a model of psoriasis, Pla2g2d−/− mice display more severe epidermal hyperplasia than do Pla2g2d+/+ mice, with increased IL-17A+ or IL-22+ T cells in the affected skin and LNs." (PMID 30546811, 2018). "In this article, the immunologic role of IL-17 in psoriasis and psoriatic arthritis (PsA) pathogenesis, including its role in innate and adaptive immunity, and the rationale for targeting IL-17A, IL-17F, and IL-17 receptor A in the treatment of psoriasis and PsA, are reviewed." (PMID 30109481, 2018). "After this stimulation, the downstream effector molecules of Th17 cells, including IL-17A, IL-22, TNF-α, and IL-6 are produced in response to certain stimuli and subsequently induce keratinocyte proliferation and other hallmark features of psoriasis." (PMID 28900461, 2017). "Compared with secukinumab and ixekizumab that target IL-17A alone, the ability of brodalumab to block the effects of more IL-17 cytokines involved in psoriasis by interacting with IL-17RA may contribute to higher efficacy." (PMID 29104241, 2017).
psoriasis (continued). "However, the IL-17A/IL-23 axis was still emphasized as an important factor in the treatment of psoriasis." (PMID 28761880, 2017). "This study showed that key features of the cutaneous phenotype generated by Aldara (5% IMQ) are influenced by strain and sex, including features related to central aspects of psoriasis lesion development, such as epidermal proliferation, IL-17A signaling, and T lymphocyte activity." (PMID 28279190, 2017). "We examined whether macrophages are activated in the skin of imiquimod (IMQ)-treated mice, a model for IL-17A-induced psoriasis-like skin inflammation, and flaky-tail (Flgft) mice, a model for IL-17A-induced chronic atopic dermatitis-like skin inflammation." (PMID 28963556, 2017). "IL-17a neutralizing antibody blocked mS100a7a15 expression in IMQ-induced psoriasis skin in vivo." (PMID 28060905, 2017). "Cytokines such as IL-1β, IL-17A, IL-22 and IL-23, which are involved in the pathogenesis of psoriasis, may also contribute to the production of IL-1β." (PMID 28266627, 2017). "Notably, IL-17a neutralizing antibody treatment in IMQ-induced psoriasis model decreased mS100a7a15 expression at mRNA and protein level." (PMID 28060905, 2017). "For psoriasis, it is now well established that interleukin IL-17 is involved in the formation of the skin lesions, a notion recently confirmed in humans by the success of monoclonal antibodies against IL-17A or the receptor IL-17RA in controlling and reversing the skin disease." (PMID 28216554, 2017). "Besides upstream regulation of IL-23, TNF-α can act synergistically with IL-17A on epidermal keratinocytes, resulting in overexpression of various psoriasis-related proinflammatory gene including S100A7, IL-8, DEFB4, CCL20 and CXCL1." (PMID 29232931, 2017). "We also tested whether TWEAK might function in synergy with the signature cytokines of AD and psoriasis, IL-13 and IL-17A, whose receptors are also expressed on keratinocytes." (PMID 28530223, 2017). "Considering the results for the variant encoding p.Arg381Gln in IL23R gene, we noted that Il-23R and Th17 cytokines are down-regulated after successful therapies and there are monoclonal antibodies directed against IL-12/23p40, IL-17A and IL-17RA which are effective in psoriasis." (PMID 29091937, 2017). "It has been showed that IL-1α, IL-1β, IL-17A and IL-23 are important to psoriasis progress." (PMID 28060905, 2017). "Several psoriasis-related cytokines, including IL-17a, IL-22 and IL-36γ, could up-regulate hS100A7 expression in keratinocytes." (PMID 28060905, 2017). "Antagonizing this pro-inflammatory pathway by antibodies directed against the involved cytokines such as IL-17A and IL-23 or their receptors have demonstrated clinical efficacy in psoriasis, psoriatic arthritis, autoimmune uveitis, ankylosing spondylitis and Crohn`s disease." (PMID 29155882, 2017). "Detailed knowledge of IL-17A biology in humans has led to the targeted development of immunotherapeutic monoclonal antibodies (mabs) to block IL-17A and the IL-17RA receptor for the treatment and control of psoriasis, multiple sclerosis and rheumatoid arthritis." (PMID 28388924, 2017). "Strain differences were not peripherally associated with psoriasis disease mechanisms but related to key aspects of the pathogenesis (e.g., KC differentiation, T-cell abundance, and IL-17A and type I interferon responses)." (PMID 28279190, 2017). "Analysis of the psoriasis transcriptome also reveals enrichment for IL-17A genes." (PMID 26573299, 2016). "Importantly, they also exhibited potent activity in the psoriasis-relevant keratinocyte cellular assay measuring IL-17A-stimulated production of the pro-inflammatory cytokine IL-8 (IC50 < 540 nM)." (PMID 27527709, 2016). "Secukinumab is an IL17A monoclonal antibody, with recognised efficacy in treating psoriasis." (PMID 26892034, 2016).
psoriasis (continued). "In addition to psoriasis, IL17A target genes also show close relatedness with signature disease genes of other indications, such as IBD, COPD, dermatitis, lupus, and arthritis." (PMID 27089880, 2016). "Hallmark pathways of psoriasis were analysed and among the cytokines IL-17A and IL-17F were elevated in the absence of IL-12Rβ2." (PMID 27892456, 2016). "Here, we report that IL-17A signaling leads to cholesterol accumulation in keratinocytes which might be playing a crucial role in psoriasis pathophysiology." (PMID 26781963, 2016). "Elevated cholesterol levels by IL-17A may be a reason for subclinical alterations of the epidermal skin in psoriasis." (PMID 26781963, 2016). "Secukinumab targeting IL-17A is also recently approved to treat psoriasis." (PMID 26843788, 2015). "Our findings are indicative of a neutrophil–keratinocyte axis in psoriasis that may involve neutrophil-derived IL-17 and is an early target of IL-17A-directed therapies such as secukinumab." (PMID 25828362, 2015). "However, no elevated serum IL-17A levels were detected in different cohorts of psoriatic patients, although Th17 cells, which produce IL-17, were noted to play an important role in psoriasis." (PMID 26362816, 2015). "In light of that, a natural compound like RSV, which might increase the RXR gene expression and decrease IL-17A, IL-17F and IL-19 gene expression in psoriasis-affected skin, could be an interesting new treatment modality in human clinical trials." (PMID 25965695, 2015). "Some researchers have recently shown that IL-17A and/or IL-17F are responsible for development of inflammation in many disorders, especially in autoimmune diseases like rheumatoid arthritis (RA), psoriasis, juvenile idiopathic arthritis (JIA), Crohn’s disease and many others." (PMID 26062902, 2015). "However, we noted disparities between DEGPs that are most and least psoriasis-specific, with only the former induced by IL-17A in cultured KCs." (PMID 26251673, 2015). "Only psoriasis-specific DEGPs, for example, were enriched with IL-17A targets." (PMID 26251673, 2015). "Therapies targeting IL-17A were approved recently for clinical use in psoriasis." (PMID 26336150, 2015). "Pathway “Role of IL-17A in Psoriasis” was enriched in both LP-C and NLP-C comparisons." (PMID 25897967, 2015). "In addition, “Agranylocyte adhesion and diapedesis” (p = 6.08E-13) and “Role of IL-17A in Psoriasis” (p = 8.52E-11) were two other highly enriched canonical pathways in LP compared to C sample." (PMID 25897967, 2015). "The clinical efficacy of ustekinumab – an anti-p40 monoclonal antibody that blocks IL-12 and IL-23 – and antibodies directed against IL-17A and the IL-17 receptor A chain has been taken as evidence that the IL-23/Th17 axis is indeed central to the pathophysiological cascade of psoriasis 4–9." (PMID 25828362, 2015). "In the past decade, Th1 cytokines such as interferon-γ (IFN-γ) and tumor necrosis factor-α (TNF-α) were considered to play a major role in this disease, but recent evidence points toward a central role of IL-23 and IL-17A in the physiopathogenesis of psoriasis." (PMID 26351408, 2015). "Neutrophils and MCs are other significant potential sources of IL-17A in psoriasis." (PMID 24904581, 2014). "In psoriasis IL-17A, IL-17F, IL-22 and IL-20 act on keratinocytes leading to epidermal hyperplasia." (PMID 25153527, 2014). "Even with the large number of genes differentially expressed, only 3 canonical pathways reached significance of p<0.05 at 24 h p.i., including Role of IL-17A in Psoriasis (p = 0.0136), RAN Signalling (p = 0.0178) and Role of RIG1-like Receptors in Antiviral Innate Immunity (p = 0.0454; Tab." (PMID 24618842, 2014). "New cytokines and T cells populations, as IL-17A, IL-22, and Th22 cells, could play an important pathogenetic role in psoriasis and IBD." (PMID 23971052, 2013).
psoriasis (continued). "Experimental data show that imiquimod (IMQ)-induced dermatitis in mice closely resembles human psoriasis lesions not only with regard to phenotypic and histological characteristics but also in the development of the lesions, which is based on the IL-23/IL-17A axis." (PMID 23825622, 2013). "IL-17A and IL-17F, the two signature cytokines collectively referred to as IL-17 in the following, have attracted much attention owing to their pathological potential and their ability to promote autoimmune diseases such as psoriasis and rheumatoid arthritis." (PMID 24348243, 2013). "The lower levels of the AMP-inducers IFN-γ and IL-17A may contribute to the observation that the induction of AMP in atopic dermatitis is less pronounced as compared to the AMP induction seen in psoriasis." (PMID 23555696, 2013). "Indeed, an IL-17A-specific antibody was efficacious in clinical trials of human psoriasis, uveitis, and rheumatoid arthritis." (PMID 23437182, 2013). "In addition, we studied IL-9R expression in psoriatic skin lesions and on CD4+ T cells and the effect of IL-9 on IL-17A production in cultured human peripheral blood mononuclear cells or CD4+ T cells from psoriasis patients." (PMID 23335955, 2013). "Analysis of this list of DEGs in IPA indicated that several well-known key cytokine pathways (e.g., IL-17 and IFNγ) and pathways of great importance such as Role of IL-17A in Psoriasis, Atherosclerosis Signaling, and Fatty Acid Metabolism were significantly represented in the DEGs list." (PMID 22957057, 2012). "Through the secretion of IL-17A and proinflammatory cytokines, Th17 cells are critical players in the pathophysiology of RA and other inflammatory disorders, such as inflammatory bowel disease, psoriasis, and allograft rejection." (PMID 23055831, 2012). "The critical role of CCR6 in psoriasiform inflammation was well documented by the observation of expression of CCR6 and CCL20 in psoriatic lesions and by the finding that both IL-17A- and IL-22-producing cells isolated from lesional skin of patients with psoriasis displayed CCR6." (PMID 21311769, 2011). "As was the case with IL-17Apos CD8 T cells, also the percentage of IL-22pos CD8 T cells was much higher in the epidermis than in the adjacent dermis of psoriatic skin, but not in normal skin, underlining a possible role of IL-17A and IL-22 producing CD8 T cells in the pathogenesis of psoriasis." (PMID 21124836, 2010). "All these results point to a prominent role for the IL-23/IL-17A pathway in the etiology of psoriasis, and many investigators have speculated about a principal role for Th17 cells in particular." (PMID 21124836, 2010). "Previous studies have shown synovial membrane mRNA levels of IL-17A may predict joint damage progression in RA and IL-17A serum levels correlate with disease severity in psoriasis patients." (PMID 19627579, 2009). "Similarly, while the observed increase in circulating IL-17A aligns with the expected pharmacology of IL-17RA blockade, no patient-level studies have directly demonstrated receptor-mediated cytokine accumulation in psoriasis." (PMID 41516330, 2026). "Therefore, the factors, including IL-17A, IL-22, IL-1β, NLRC4, MEFV, and CASP5, detected by ocular surface test in our case should be verified for their usefulness as biomarkers for psoriasis-associated conjunctivitis in clinical studies involving a large number of cases." (PMID 40861543, 2025). "Notably, differential expression analysis identified 1,530 up-regulated and 1,435 down-regulated genes in the PLEVP group compared to the model, with several psoriasis-related inflammatory markers (Il17a, Ccl2, Cxcl2, and Tnf) being significantly down-regulated." (PMID 40248109, 2025). "Furthermore, S100A8 and S100A9 may inhibit psoriasis by prohibiting the synthesis of IL-17A and IL17-F." (PMID 40540498, 2025).